AR (androgen receptor)
Diseases named in the same sentence as AR in open-access papers (continued):
Sharing a sentence is not in itself a finding about the gene and the disease.
Gynecomastia (26 papers, 2009 to 2025). Abnormal development of large mammary glands in males resulting in breast enlargement. "Enzalutamide, an androgen receptor signaling inhibitor was shown to be associated with a 49% rate of gynecomastia within 2 years." (PMID 33275817, 2021). "As young men, those with an AR mutation tended to have a worse prognosis for virilization as reflected by the gynecomastia." (PMID 27403927, 2016). "The gynecomastia, which was universally encountered in all the young men with an AR mutation, confirms previous reports." (PMID 27403927, 2016). "Six men had gynecomastia that was severe enough to require mastectomy; five (83%) of these six men had an AR mutation." (PMID 27403927, 2016). "Spironolactone has low selectivity for the MR vs. AR (~ threefold more selective for the MR vs. AR), which means it has greater potential to block ARs, which is associated with sexual side effects such as gynecomastia, especially at higher doses." (PMID 40448875, 2025). "The use of enzalutamide, an androgen receptor signaling inhibitor, besides binding to the androgen receptor inhibiting also DNA binding and coactivator recruitment, has likewise been shown to be associated with a 49% rate of gynecomastia and 21% rate of nipple pain within 2 years." (PMID 32166452, 2020). "Our findings highlight the potential therapeutic relevance of targeting pathways involved in growth factor signaling (e.g., IGF1R and TGFB1), androgen receptor modulation and melanocortin signaling for managing gynecomastia." (PMID 40002676, 2025). "Ten key genes associated with gynecomastia were identified, including IGF1, TGFB1 and AR, alongside 12 candidate drugs with promising binding affinities, such as yifenidone, conteltinib and vosilasarm." (PMID 40002676, 2025). "In contrast, our study noted a significant positive correlation between AR and PR (0.281, p=0.005), indicating that the relationship between biomarkers within gynaecomastia is distinctly different from malignant male breast lesions." (PMID 35814372, 2022). "It activates the progesterone receptor (PR) and inhibits the androgen receptor (AR) to a significant extent, leading to cycle irregularities in female patients and gynecomastia in male patients." (PMID 36293446, 2022). "Although it was found to accelerate the degradation of AR, it has estrogenic effects, inducing gynecomastia for men with monotherapy, paradoxically stimulating the occurrence of late-stage PCa." (PMID 35164166, 2022). "We report a predominance of various types of nuclear steroid receptors in gynaecomastia with over two thirds of the lesions expressing androgen receptor." (PMID 35814372, 2022). "Spironolactone binds the androgen receptor and induces gynecomastia in men and amenorrhea in premenopausal women." (PMID 35551674, 2022). "Androgen receptor inhibitors revealed several adverse events as decreased libido, erectile dysfunction, ejaculatory dysfunction, and gynecomastia." (PMID 34466348, 2021). "Side effects come along with its affinity to androgen receptor leading to gynecomastia and erectile dysfunction in male and to progesterone receptor leading to menstrual irregularity in female." (PMID 33995277, 2021). "Given that these men have severe and persistent gynecomastia that is more likely to lead to mastectomy, early knowledge of AR genetic status would allow the provision of informed guidance to the adolescent." (PMID 27403927, 2016). "Immunohistochemical staining for PSA, PSAP, AR, ER, and PR was performed on tissue microarrays representing six cases of gynecomastia, thirty MBC, and fifty-six FBC." (PMID 20863373, 2010). "The effect of the AR repeat expansion is androgen insensitivity with gynecomastia and decreased fertility and motor neuron degeneration which may lead to increased testosterone levels." (PMID 35132468, 2022).
Gynecomastia (continued). "However, our study population has shown a lack of knowledge regarding the drugs that are attributed to gynecomastia development; with antihypertensives being least among other medications, and androgen receptor blockers being highest in the list." (PMID 33643766, 2021). "Therefore, androgen receptor modulators show potential therapeutic effects on gynecomastia." (PMID 40002676, 2025). "Furthermore, spironolactone exhibits anti-androgenic effects due to its activity as a progesterone receptor agonist and androgen receptor antagonist, which can result in gynecomastia, breast tenderness, menstrual irregularities, impotence, and decreased libido, especially at higher doses." (PMID 39518537, 2024). "In addition, spironolactone has a similar structure to progesterone and acts as a progesterone receptor (PR) agonist and androgen receptor (AR) antagonist, therefore promoting sexual side effects including gynecomastia and impotence in men and disruption of the menstrual cycle in women." (PMID 36768761, 2023). "All cases with an AR mutation had gynecomastia, compared to 9% of those without an AR mutation." (PMID 27403927, 2016). "All men with an AR mutation had gynecomastia, compared to only 10% of men without a mutation." (PMID 27403927, 2016). "The AR expression shown in this study supports the use of non-aromatising androgen therapies, such as dihydrotestosterone, which has shown good response rates in patients with prolonged pubertal gynaecomastia." (PMID 35814372, 2022). "However, due to functional AR activity, gynecomastia has not been reported in cases with 5α-reductase type 2 deficiency and partial gonadal dysgenesis." (PMID 27087292, 2016).
osteoporosis (26 papers, 2009 to 2025). A condition of reduced bone mass, with decreased cortical thickness and a decrease in the number and size of the trabeculae of cancellous bone (but normal chemical composition), resulting in increased fracture incidence. "In summary, androgen receptor gene alteration and total cholesterol are associated with osteoporosis in elderly Han men." (PMID 36815982, 2023). "Quantitative analysis showed that osteoporosis caused a significant decrease in protein expressions of AR and ER in femur compared to normal control group (P < 0.01)." (PMID 25648166, 2015). "Androgen receptor LL genotype and elevated total cholesterol may be the risk factors for osteoporosis in older men of Han nationality." (PMID 36815982, 2023). "For example, genetic variants of the androgen receptor may contribute to variation in bone mass as well as to predisposition to osteoporosis." (PMID 20021635, 2009). "It is possible that increased hnRNPK in osteoblasts from Prdx5Ko can reduce AR expression levels, leading to osteoporosis in Prdx5Ko mice." (PMID 36735291, 2023). "Proteins of AR and ER were strongly expressed in normal control group, while the two receptors were weakly expressed in osteoporosis rats." (PMID 25648166, 2015). "Selective androgen receptor modulators (SARMs), designed to treat conditions such as muscle wasting and osteoporosis, are widely used among healthy adults seeking muscle hypertrophy and enhanced athletic performance, despite a lack of Food and Drug Administration (FDA) approval." (PMID 39421081, 2024). "Effect of androgen receptor (CAG)n genotype on osteoporosis." (PMID 36815982, 2023). "Finally, this study only discussed the effect on osteoporosis in terms of genotypes, and the specific mechanism of androgen receptor on bone mineral density needs to be further studied." (PMID 36815982, 2023). "Androgen receptor (AR) has been shown to be of relevance for a group of hormone-related diseases, as well as for synthetic metabolic defects such as muscle atrophy and osteoporosis." (PMID 35736181, 2022). "Therefore, we explored the effects of the androgen receptor CAG repeat sequence on osteoporosis." (PMID 36815982, 2023). "For instance, in KS patients neither T levels nor polymorphisms in the androgen receptor (AR) gene - consisting of a variable number of CAG repeats which modulate its sensitivity - are associated with osteoporosis, thus pointing to a potential impact of high FSH levels." (PMID 35992104, 2022). "Finally, the application of selective androgen receptor modulators may provide new approaches for the treatment of osteoporosis and fractures as well as building stronger bones in diseases dependent on androgens/AR status." (PMID 31731497, 2019). "Taken together, these results substantiate that AR/PCC extracts could improve innervation and angiogenesis within the vertebral bodies of DM rats, thereby resisting the progression of osteoporosis." (PMID 37621124, 2023). "Recently, the application of non-steroidal selective androgen receptor modulators (SARMs) has been suggested for the treatment of osteoporosis and frailty." (PMID 32876707, 2020). "More importantly, we provide compelling evidence demonstrating that the sex differences are closely related to AR, MAPK, and ECM related signaling, unveiling an important role for PKC-δ in the pathogenesis of osteoporosis in animal models, cell culture, and molecular interactions." (PMID 32582715, 2020). "According to the relevant literature, the effects of AR and CTNNB1 have already been studied well in the related studies, while the effects of PIK3CA still remain unclear in osteoporosis." (PMID 40236832, 2025). "Moreover, the role of androgen receptor genotypes in the pathogenesis of osteoporosis is unclear; therefore, this study discusses the relationship between androgen receptor CAG gene alteration and osteoporosis." (PMID 36815982, 2023).
cervical carcinoma (25 papers, 2005 to 2025). A carcinoma arising from either the exocervical squamous epithelium or the endocervical glandular epithelium. "In recent years, ARs have been found to be closely associated with the occurrence and progression of cancers of the female reproductive system; loss of AR expression is commonly observed in cervical cancer." (PMID 39274874, 2024). "Some other studies have shown DSG2, PLOD2, ANLN, AURKA, and AR genes might be key genes associated with cervical cancer progression." (PMID 41266827, 2025). "For instance, miR-130a-3p promotes cervical cancer cell proliferation and invasion by targeting estrogen receptor α and androgen receptor." (PMID 41361055, 2025). "The pronounced sensitivity of HeLa cervical cancer cells, combined with computational predictions of stable spathulenol-AR interactions, suggests particular therapeutic promise for hormone-dependent malignancies." (PMID 41155656, 2025). "In cervical cancer, the overexpression of the AR significantly inhibits the proliferation of cervical cancer cells." (PMID 40729027, 2025). "hsa‐miR‐130a‐3p directly targets ERα and AR, upregulation contributes to tumor progression, inhibition of miR‐130a‐3p, and overexpression of AR and ERα inhibits cervical cancer invasion and proliferation." (PMID 39185567, 2025). "By specifically targeting ER and AR, miR-130a-3p promoted cervical cancer cell invasion and proliferation." (PMID 38523927, 2024). "PIAS2 interacts with UXT protein, an important co-regulator of transcription factors such as androgen receptor (AR), in the cytoplasm and nucleus of human cervical carcinoma." (PMID 38590645, 2024). "Taken together, miR-130a-3p has a possible role in the progression of cervical cancer, through the suppression of ERα and AR." (PMID 34831421, 2021). "MiR-130a-3p silencing, ERα up-regulation, and AR up-regulation have suppressed proliferation and invasion of cervical cancer cells." (PMID 34831421, 2021). "Consistently, we found that AR was underexpressed in cervical cancer and was significantly related to poor clinical prognosis, providing insights concerning a potential role of AR in cervical carcinogenesis." (PMID 32258155, 2020). "A previous study has shown that AR expression is frequently decreased or lost in advanced cervical cancer versus normal cervix epithelium." (PMID 32258155, 2020). "The patients with cervical cancer show a higher proportion of AR expression in epithelial cells of the ovary, which is statistically significant (P < 0.01) compared with patients with other proliferative diseases." (PMID 24279585, 2013). "Although microRNA (miR) 130a3p expression levels were higher in cervical cancer tissues compared to healthy tissues, ER and AR expression decreased sequentially from healthy cervical tissues to cervical intraepithelial neoplasia tissues to cervical cancer tissues." (PMID 38523927, 2024). "In cervical cancer, the oncogenic miR-130a-3p has been found to target both ERα and AR." (PMID 34831421, 2021). "However, the role of expression alterations of AR in relation to cervical cancer is not well understood." (PMID 32258155, 2020). "Therefore, extensive studies will be required to corroborate the relationship of cervical carcinoma with androgen receptor expression." (PMID 24279585, 2013). "Although wild-type HeLa cervical cancer cells are both PR and AR negative, T47D-Y (PR-negative) cells did express low levels of endogenous AR by western blot." (PMID 16457685, 2005).
osteosarcoma (25 papers, 2015 to 2026). A usually aggressive malignant bone-forming mesenchymal neoplasm, predominantly affecting adolescents and young adults. "Further analysis revealed a close association between high expression of YAP and AR and the clinical features of osteosarcoma, particularly in relation to advanced tumor stage and metastatic status." (PMID 41517748, 2026). "This study investigates the expression of Yes-associated protein (YAP) and androgen receptor (AR) in osteosarcoma and assess their prognostic significance." (PMID 41517748, 2026). "In summary, this study reveals a close association between high expression of YAP and AR and the malignant progression of osteosarcoma." (PMID 41517748, 2026). "The combined expression of YAP and AR significantly intensified the risk of disease progression in osteosarcoma patients." (PMID 41517748, 2026). "YAP and AR expression showed a significant positive correlation in osteosarcoma, with the strength of this association varying by clinical characteristics." (PMID 41517748, 2026). "High expression of YAP and AR was significantly associated with aggressive clinical features of osteosarcoma." (PMID 41517748, 2026). "High expression of YAP and AR was significantly associated with reduced PFS in patients with osteosarcoma." (PMID 41517748, 2026). "We next examined the expression of AR in patient tumor tissue and its potential diagnostic value in clinical osteosarcoma." (PMID 28262798, 2017). "Because the expression of DBC1 and AR were associated with the proliferation and invasion activity of osteosarcoma cells, we evaluated the expression of DBC1, AR, and the molecules related with the proliferation and invasiveness of cells." (PMID 26249023, 2015). "Furthermore, we determined the effects of AR specific inhibitor bicalutamide (also known as casodex) on osteosarcoma cells and interrogated the underlying mechanism of CDK11 and AR gene network in osteosarcoma." (PMID 28262798, 2017). "By analyzing the expression patterns of YAP and AR in osteosarcoma tissues and exploring their associations with clinicopathological features, this study seeks to determine whether a synergistic interaction exists between the two, jointly promoting tumor progression and metastasis." (PMID 41517748, 2026). "Through systematic immunohistochemical analysis and clinical follow-up, this study comprehensively explored the expression characteristics and clinical significance of YAP and AR in osteosarcoma, yielding several key findings." (PMID 41517748, 2026). "High expression of YAP (65%) and AR (60%) was significantly more frequent in osteosarcoma than in normal tissues." (PMID 41517748, 2026). "Firstly, we found that the expression levels of YAP and AR were significantly higher in osteosarcoma tissues compared to normal bone tissues (P < .001)." (PMID 41517748, 2026). "This study is the first to systematically evaluate the combined expression of YAP and AR in osteosarcoma." (PMID 41517748, 2026). "Interaction analysis confirmed a significant synergistic oncogenic effect between YAP and AR in osteosarcoma." (PMID 41517748, 2026). "The expression levels of YAP and AR were significantly higher in osteosarcoma tissues compared to normal bone tissues." (PMID 41517748, 2026). "YAP and AR are frequently co-overexpressed in osteosarcoma and jointly contribute to tumor aggressiveness and unfavorable outcomes." (PMID 41517748, 2026). "As an AR coactivator, CCAR2 promotes AR transcriptional activity by enhancing its DNA-binding activity and its stability in prostate cancer and osteosarcoma cells." (PMID 37524873, 2023). "Here, we set out to study the mechanisms that endow AR and GR with unique functions by examining human osteosarcoma cell lines that express either GR or AR." (PMID 33751115, 2021).